KRAS (KRas proto-oncogene, GTPase)
Diseases named in the same sentence as KRAS in open-access papers (continued):
Sharing a sentence is not in itself a finding about the gene and the disease.
colon (34 papers, 2006 to 2026). "KRAS mutations are present in a wide fraction of tumors beyond those of the lung, including gastrointestinal tumors with dismal prognosis such as those of the pancreas and the colon." (PMID 37816716, 2023). "Here, we present two KRAS-mutated wild-type gastrointestinal tumours (GISTs)." (PMID 37663588, 2023). "We and others have previously demonstrated that STAT3 signaling in response to IL-6 family cytokines provides a rate-limiting signal for gastrointestinal tumors that arise from bona fide oncogenic driver mutations, including in APC, KRAS, or other genes." (PMID 39128004, 2024). "On the other hand, KRAS was mutually exclusive with LRP1B in the left-side colon tumors, while the result was not significant in other sites." (PMID 36439454, 2022).
hematologic malignancies (18 papers, 2016 to 2026). "In contrast, detected variants in hematologic malignancies were merely seen in the KRAS gene." (PMID 33083132, 2020). "Subgroup analysis showed the strongest effects in hematological malignancies (g = 0.85), particularly in studies targeting oncogenes such as KRAS, MYC, and PIK3CA." (PMID 41517680, 2026). "For instance, KRAS and NRAS mutations are found in about 5–26% of hematologic diseases, and RAS mutation has been observed in 16% of AML and 5% of MDS patients." (PMID 39770471, 2024). "Compared with iPSC-based modeling of hematologic malignancies that typically contain multiple mutated oncogenes, our RALD-iPSCs acted as an invaluable tool to investigate the considerable effect of KRAS (G13C) on cellular functions within an isogenic HPC pair." (PMID 38627844, 2024). "NGS covering 51 genes related to hematological malignancies revealed NRAS-p.Gly12Asp, PTPN11-p.Asp61Val, PTPN11-p.Thr468Met, KRAS-p.Gly12Val, and CALR-p.Gly108Arg mutations." (PMID 35912172, 2022). "In summary, the data suggest NLRP3 and IL-1R inhibition as a strategy for the treatment of KRAS-driven hematological malignancies." (PMID 32246016, 2020). "KRAS is an oncogene in the Ras-MAPK signaling pathway, and mutations within this gene have been associated with leukemogenesis and hematologic malignancies." (PMID 26527318, 2016). "For KRAS-driven hematological malignancies, a therapeutic approach might include the use of NLRP3 and IL-1R suppressors." (PMID 36902299, 2023). "Also, other hematologic malignancies are reportedly associated with KRAS (G12D) or KRAS (G13D), not with the KRAS (G12C) mutation." (PMID 38627844, 2024).
benign tumors (13 papers, 2013 to 2026). "It is possible that patients with benign tumours and KRAS mutation from pancreatic exocrine secretions go on to develop PDAC, however, there was insufficient long-term follow-up in the included studies to enable this to be investigated." (PMID 32825312, 2020). "KRAS mutations are rarely detected in the plasma of patients with benign neoplasms." (PMID 29451897, 2018). "Testing for the KRAS mutation might be useful in predicting the progression of a benign tumor into a malignant one." (PMID 24891964, 2014). "Notably, KRAS mutations, HRAS mutations, and HPV infection were mutually exclusive in benign neoplasms of the head and neck." (PMID 35600380, 2022).
blood cancer (11 papers, 2015 to 2026). "Since some AML cell lines harbor SOS1 mutations and are dependent on SOS1 for survival, a combination of SOS1 and MEK inhibitors may be an attractive strategy for the treatment of blood cancers containing KRAS mutations." (PMID 33801965, 2021). "These KRas mutations are found at much higher rates than Ras mutations in blood cancer overall." (PMID 34680208, 2021). "Some of these biases were expected (e.g., KRAS in gastrointestinal cancers or JAK2 in blood cancers)." (PMID 41465353, 2025). "Similar oncogenic alterations in KRAS, NRAS and HRAS genes are strong causative drivers in a broad variety of solid and hematological tumors with mostly aggressive behavior." (PMID 34771672, 2021). "Investigations into the aberrant expression of miR-155, Kirsten Rat Sarcoma Viral Oncogene Homolog (KRAS), and cAMP Response Element-Binding Protein (CREB) in AML patients have provided valuable insights into the molecular landscape of this blood cancer." (PMID 39512697, 2024).
hematologic cancers (9 papers, 2012 to 2026). "Notably, LZTR1 is ineffective against KRAS A146 gain-of-function mutations, which are adjacent to T148 and prevalent in hematologic cancers." (PMID 41542462, 2026). "Strong synergy is seen in neuronal, renal, breast, lung, and haematopoietic cancer cells harboring abnormalities in PTEN, VHL, LKB1, Her2, or KRAS." (PMID 23155392, 2012). "T148 phosphorylation preferentially protects KRAS and NRAS from degradation in hematologic cancers." (PMID 41542462, 2026).
colonic polyps (7 papers, 2011 to 2021). "More than 65 years of age, history of colon polyps, KRAS gene mutation, new tumors after initial treatment were found to be risk factors for the prognosis of CRC, and dMMR is a protected factor by the univariate and multivariate cox regression." (PMID 34526059, 2021).
inflammation (6 papers, 2017 to 2024). Aberrant reaction of the microcirculation characterized by movement of fluid and leukocytes from the blood into extravascular tissues. "It is plausible that in the presence of oncogenic KRAS these lipid changes locally in the pancreas in KC;Hsl−/− mice are driving promotional factors of pancreatic inflammation and PDAC development." (PMID 30086728, 2018). "Thus, gastric inflammation is necessary for metaplastic pit cell development in Hp+KRAS+ mice and is primarily comprised of increased gastric macrophages and T cells." (PMID 37674528, 2023).
neurodevelopmental disorder (5 papers, 2018 to 2025). A behavioral and cognitive disorder with onset during the developmental period that involves impaired or aberrant development of intellectual, motor, or social functions. "Next, we assessed whether excitatory neurons also contribute to the phenotypes in KRAS mutations-associated neurodevelopmental disorders." (PMID 33082413, 2020).
cardiovascular disease (4 papers, 2018 to 2022). "The KRAS belongs to the Ras gene family, and the role of KRAS in cardiovascular disease was less studied." (PMID 36704339, 2022).
metabolic disorders (3 papers, 2021 to 2024).
bacterial infection (2 papers, 2020 to 2024). "The two bacterial infections could be distinguished from IAV infection by weaker induction of type I and type II IFN signaling, but stronger enrichment of signaling pathways such as IL2_Stat5_signaling, IL6_STAT3 signaling, programmed cell death, and KRAS signaling (upregulated genes)." (PMID 39395995, 2024).
Head and neck tumors (2 papers, 2012 to 2025). "Head and neck tumors present mutations in KRAS and BRAF, but in very low frequencies, with 6% of the patients carrying a mutation in KRAS and 3% in BRAF." (PMID 23207070, 2012).
neurologic disease (2 papers, 2022 to 2024). "Recent studies have identified NRAS, KRAS, MAP2K1, and ARAF mutations in RDD patients without documented neurologic disease." (PMID 35236371, 2022).
epithelial neoplasm (1 paper, 2023). A benign or malignant neoplasm that arises from and is composed of epithelial cells. "For example, PanIN, a microscopic noninvasive epithelial neoplasm, showed >90% KRAS mutations in the all-grade dysplasia of PanIN, whereas no mutation was observed in normal pancreatic duct samples." (PMID 36673023, 2023).
gynecological tumors (1 paper, 2020).
KRAS also shares sentences with these, for which no sentence is quoted: dengue (83 papers); ZIKV infection (50); Cirrhosis (24); hepatitis C (18); chronic hepatitis C (13); liver fibrosis (8); type 2 diabetes (7); anaplastic carcinoma (6); encephalitis (6); carcinoma in situ (5); genetic disease (5); influenza (5); breast adenocarcinoma (4); chronic kidney disease (4); co-infection (4); Dengue hemorrhagic fever (4); follicular adenoma (4); neurofibromatosis (4); polycystic kidneys (4); serous borderline ovarian tumors (4); urachal carcinoma (4); uterine corpus endometrial carcinoma (4); uterine endometrioid carcinoma (4); adenoid cystic carcinoma (3); benign ovarian tumours (3); chronic hepatitis (3); cutaneous squamous cell carcinoma (3); embryonal rhabdomyosarcoma (3); Flavivirus Infections (3); liposarcoma (3).
A further 312 diseases each share a sentence with KRAS in 3 papers or fewer.